ALKBH5 (alkB homolog 5, RNA demethylase)
Diseases named in the same sentence as ALKBH5 in open-access papers (continued):
Sharing a sentence is not in itself a finding about the gene and the disease.
tumor (continued). "Decreased expression of ALKBH5 leads to increased 3′UTR m6A modification of LYPD1 mRNA, which in turn results in the increased expression of LYPD1, which promotes tumor cell growth, migration, invasion and metastasis." (PMID 35784761, 2022). "Recently, a vital study reported that ALKBH5 elevated in GBM stem cells and maintained tumor initiation through FOXM1 expression and cell proliferation." (PMID 35572524, 2022). "These bioinformatics data support our findings that ALKBH5 plays an oncogenic role in HNSCC and promotes tumor proliferation and migration dependent on m6A modification." (PMID 35395767, 2022). "Our study found that overexpression of ALKBH5 inhibits IFNα secretion through RIG-I, reduces the infiltration of immune-killing cells, and then promotes tumor immune escape." (PMID 35395767, 2022). "ALKBH5 exhibited nuclear localization, and high level of ALKBH5 is observed in LSCC compared with non‐tumour tissues." (PMID 34850551, 2022). "Mechanistically, ALKBH5 regulates the expression of Mct4/Slc16a3 and the content of lactate in the TME, thus suppressing the composition of tumor-infiltrating Treg cells as well as MDSCs, and finally regulating the response of PD-1 immunotherapy." (PMID 35254013, 2022). "Recent researches have shown that ALKBH5 and METTL3 can be regulated by epigenetic modification of their promoters in tumor progression." (PMID 35304463, 2022). "It is found that ALKBH5 is closely related to the expression of FOXM1, regulating the level of FOXM1 methylation and tumor progression in many tumors." (PMID 35022030, 2022). "ALKBH5 regulates downstream signal transduction through the methylation of RIG-I, which ultimately affects the secretion of IFNα in tumor cells." (PMID 35395767, 2022). "The protein expression levels of ALKBH5 in 86 paired LSCC and non‐tumour tissues were detected by IHC." (PMID 34850551, 2022). "ALKBH5 regulates m6A density and splicing event during ICI treatment in the TME (tumor microenvironment)." (PMID 36439186, 2022). "Another specific inhibitor of ALKBH5, ALK-04, reduces Treg cell and MDSC infiltration and enhances the efficacy of anti-PD-1 therapy against tumor growth." (PMID 35794625, 2022). "Molecularly, ALKBH5 reduced YAP activity by regulating the miR-107/LATS2 axis in a HuR-dependent manner, further inhibiting tumor growth and metastasis in vivo." (PMID 35484099, 2022). "To further validate the results, we obtained 60 paired tumor tissues and adjacent normal tissues of ESCC, and qRT-PCR was used to determine the expression pattern of METTL3, METTL14, WTAP, FTO, ALKBH5, YTHDF1 and YTHDF2." (PMID 35399719, 2022). "The final results of this study demonstrated that ALKBH5 shRNA-loaded BMSC-Exos inhibited TNBC cell stemness and retarded tumor growth and metastasis in mice." (PMID 36551544, 2022). "We determine that ALKBH5 expression is downregulated in CRC and plays a crucial tumour suppressive role." (PMID 35979628, 2022). "Although most reports showed that ALKBH5 is an oncogene in NSCLC another work reported its tumor suppressive role in NSCLC." (PMID 35063010, 2022). "BMSC-Exos suppressed the tumor stemness, growth and metastasis of TNBC cells and ALKBH5 shRNA-loaded BMSC-Exos showed a more significant suppressive role." (PMID 36551544, 2022). "The in vivo role of ALKBH5 was confirmed, and tumor xenograft models were constructed by subcutaneously injecting HCC cells with either stable knockdown (shALKBH5 #1, #2) or overexpression of ALKBH5 (ALKBH5-OE) into nude mice." (PMID 35982895, 2022). "As a result, ALKBH5-mediated YAP1 demethylation negatively regulates YAP1 translation and inhibits the growth of tumor cells in NSCLC." (PMID 35063010, 2022). "At present, the studies regarding ALKBH5, FTO genes were mainly focused on cancer, and ALKBH5, FTO had been identified as important malignant regulators of tumor cell phenotypes and therapeutic responses." (PMID 36619747, 2022).
tumor (continued). "While ALKBH5-overexpression and SAV1-silencing group showed significantly delayed tumor growth and progression." (PMID 35414790, 2022). "declared that ALKBH5 also increased the expression of WIF-1 (Wnt inhibitory factor 1) and inhibited the Wnt pathway to suppress these tumor features." (PMID 36686788, 2022). "In tumor immunity, YTHDC1, YTHDC2 and ALKBH5 were the most correlated regulatory factors of m6A with immune cell subtypes, and YTHDC1 and YTHDC2 were positively correlated with the selected anti-tumor immune genes." (PMID 34737950, 2021). "This study identified a broad upregulation of these genes in tumor samples as compared to normal tissues, with significant increases in METTL3, METTL14, KIAA1429 (VIRMA), YTHDF1, YTHDF2, ALKBH5, FTO, WTAP, RBM15, and HNRNPC." (PMID 34209046, 2021). "In particular, they found that high expression of ALKBH5 and, in particular, another m6A reader, HNRNPA2B1, correlated with tumor diameter and lymphatic metastasis and promoted disease by upregulating fatty acid synthesis enzymes, ACLY and ACC1." (PMID 34209046, 2021). "To define ALKBH5 expression pattern in HBV-HCC, we collected 20 pairs of tumor and peri-tumor tissues with HBV infection history from Chinese patients." (PMID 34112124, 2021). "FTO and ALKBH5 act as an m6A demethylase, their inhibitors such as Rhein, meclofenamic acid (MA) and IOX3 have been identified as effective anti-tumor drugs." (PMID 34051847, 2021). "A study demonstrated that m6A demethylase (“eraser”) ALKBH5 inhibits LATS2/miR-107-mediated YAP activity and inhibits tumor proliferation and metastasis through decreasing the m6A-binding proteins YTHDFs-associated YAP expression in NSCLC." (PMID 34150845, 2021). "In addition, FTO and ALKBH5 could also alter the immune microenvironment of GC tumor cells." (PMID 33718213, 2021). "Hypoxia increased ALKBH5 expression through HIF-1α, resulting in the sustaining of target gene expression and eventually enhancing the tumor stemness phenotype." (PMID 34218271, 2021). "In OC, dysregulation of ALKBH5 and FTO takes part in proliferation, apoptosis, migration, drug resistance, cancer stem cell development and tumour autophagy, contributing to the relapse of OC patients." (PMID 34895230, 2021). "In conclusion, we demonstrate that ALKBH5, which is positively regulated by epigenetic modifications of H3K27 acetylation, promotes tumor progression by inducing tumor EMT and increasing FOXM1 expression via m6A demethylation." (PMID 33428593, 2021). "In recent years, increasing studies have confirmed that m6A methylation‐related genes, such as ALKBH5, FHL2, DGCR8, YTHDF2, YTHDF3, and PICM8, were overexpressed in tumor tissues and closely related to malignant tumors." (PMID 33264518, 2021). "Next, Wilcoxon rank-sum test was conducted between tumor and normal tissues using RNA-seq data of TCGA-COAD; the tumor tissues were found to have lower ALKBH5 expression and higher YTHDF1 expression than normal tissues." (PMID 34079761, 2021). "In the present study, we found ALKBH5, one of m6A epitranscriptomics enzyme, was highly increased in HBV-HCC tissues with prognosis prediction value, and targeting ALKBH5 inhibits tumor cells’ growth and migration." (PMID 34112124, 2021). "Previously, RNA functional analysis confirm that METTL14 and ALKBH5 can regulate the expression of each other, inhibit the demethylation activity of YTHDF3, and induce aberrant m6A modification to play roles in tumour angiogenesis and metastasis." (PMID 35004679, 2021). "In this study, we demonstrated that inhibition of ALKBH5 suppresses tumor growth in vivo and that EP300-induced H3K27ac activation promotes ALKBH5 expression." (PMID 33428593, 2021). "The tumor cells exhibited a significant increase in the expression of WTAP, YTHDF2, and YTHDF3, but a reduction in the expression of FTO and ALKBH5 compared to the normal epithelial cells in the para-tumor samples." (PMID 34733841, 2021).
tumor (continued). "Consistent with these discoveries regarding m6A levels, ALKBH5 and FTO were impaired to elevate m6A modification of targeted genes and accelerate tumour progression." (PMID 34895230, 2021). "We then explored mRNA expression of the several players among different tumor subtypes and found that erasers, FTO and ALKBH5, were expressed at higher levels, compared to writers." (PMID 34683137, 2021). "ALKBH5 can modulate the Mct4/Slc16a3 expressing state and the TME’s lactate content, as well as the composing parts of tumor-infiltrating regulatory T cells (Tregs) and myeloid-derived suppressor cells." (PMID 34188972, 2021). "Further, its ability to prevent proliferation, tumorigenicity, migration, and invasion of ESCC cells confirmed its tumor-suppressive potential in ESCC cells, executed via epigenetic silencing of ALKBH5 promoter." (PMID 34491904, 2021). "Specifically, ALKBH5 regulates the expression level and lactic acid content of Mct4/Slc16a3 in the TME and the constitution of tumor infiltrating Tregs and myeloid-derived suppressor cells." (PMID 35069586, 2021). "Remarkably, when examining all tumor samples, FTO and ALKBH5 mRNA expression levels were positively correlated (rs = 0.4243, p < 0.001)." (PMID 34683137, 2021). "Conversely, several m6A regulators, such as ALKBH5 and METTL16, presented tumor-suppressing characteristics, with higher gene expression levels relating to favorable prognosis." (PMID 35046996, 2021). "The expression of ALKBH5 and FTO has been proved to be up-regulated in tumor tissues, which implies a poor prognosis of HCC patients." (PMID 34557360, 2021). "It has been reported that YAP, ALKBH5, IGF2 and other tumor suppressor elements can interact with ncRNA to inhibit tumor progression." (PMID 34188972, 2021). "By comparing 50 normal and 374 tumor tissues, METTL14, YTHDC1, ZC3H13, ALKBH5, YTHDF2, and RBM15 had extremely lower expression in tumor tissues (p < 0.001)." (PMID 34277622, 2021). "Comparisons between adjacent normal and tumor samples identified seven down-regulated (METTL14, WTAP, YTHDC1, YTHDC2, ALKBH5, FTO, and YTHDF2) and one up-regulated (YTHDF1) regulators." (PMID 32500031, 2020). "In detail, the expression of ALKBH5 was also connected with specific clinicopathological features such as TNM staging, tumor size, lymph node metastasis, and distant metastasis." (PMID 32742194, 2020). "As an important functional target of ALKBH5, FOXM1 overexpression can reverse the function of ALKBH5 or inhibit FOXM1 long noncoding RNA antisense (FOXM1-AS) and restore GSC tumour growth." (PMID 32943100, 2020). "QRT-PCR and IHC analysis showed that SOX2OT depletion significantly decreased ALKBH5 and SOX2 expression level in resected tumor tissues upon TMZ treatment in comparison with the U87TR-sh-NC group." (PMID 32439916, 2020). "In the current study, we clarified the molecular mechanism of m6A modification and function of YAP, regulated by ALKBH5 and YTHDFs proteins, in the regulation of NSCLC tumor growth and metastasis." (PMID 32106857, 2020). "To further address the anti-oncogenic role of ALKBH5 in HCC, we conducted in vivo experiments with subcutaneous tumor models." (PMID 32772918, 2020). "Functionally, ALKBH5-mediated PVT1 upregulation promoted the OS cell proliferation in vitro and tumor growth in vivo." (PMID 32021563, 2020). "Five m6A-related genes (ZC3H13, METTL14, YTHDF2, YTHDF3 and HNRNPA2B1) showed significantly downregulated in tumor tissue, while seven regulators (YTHDC2, FTO, WTAP, METTL3, ALKBH5, RBM15 and KIAA1429) was remarkably upregulated in ccRCC." (PMID 32419773, 2020). "Therefore, we speculate that, the RNA methylation regulated by YTHDC2 and ALKBH5 might regulate tumor proliferation and metastasis through HIF-mediated hypoxic microenvironment response and then affect the prognosis of patients, which would be confirmed in our future research." (PMID 32500031, 2020).
tumor (continued). "We observed that YAP expression is negatively correlated with ALKBH5 expression, which plays an opposite role in the regulation of NSCLC tumor growth and metastasis." (PMID 32106857, 2020). "ALKBH5 regulates the mRNA level of FOXM1 by reducing m6A modification, participates in the generation of intermittent hypoxia (IH) tumor microenvironment, and promotes proliferation and invasion of lung adenocarcinoma cells." (PMID 33552994, 2020). "Otherwise, ALKBH5 knockdown inhibits NANOG expression, reduces BCSC population, and impairs tumor formation in vivo." (PMID 31921664, 2019). "Blocking the downstream activation of proteins induced by hypoxia (like ALKBH5, CAIX, and NANOG) has been shown to inhibit CSC expansion in the tumor site, decreasing the probabilities for tumor relapse after therapy." (PMID 28473858, 2017). "ALKBH5 overexpression downregulates KCNK15-AS1, accelerating tumor growth." (PMID 40271153, 2025). "Mechanistic studies revealed that ALKBH5 upregulated MAP3K8 expression in an m6A-dependent manner, thereby activating JNK/ERK signaling and enhancing IL-8 secretion, which recruited PD-L1+ macrophages to foster tumor growth, metastasis, and immune evasion." (PMID 41562066, 2025). "Moreover, higher expression of ALKBH5 was correlated with advanced clinical stages, International Society of Urological Pathology (ISUP) grades, metastasis and larger tumor size." (PMID 40603319, 2025). "The results indicate that during the 4-week treatment period, compared to the Control group, tumor volume and mass were significantly reduced in the ALKBH5-siRNA-BNVs group and NGR-ALKBH5-siRNA-BNVs group, with the NGR-ALKBH5-siRNA-BNVs group showing more pronounced inhibition." (PMID 40585991, 2025). "The consequent reduction in ALKBH5-mediated m6A demethylation on CD276 mRNA increases CD276 expression, facilitating immune evasion by suppressing cytotoxic T-cell activity and promoting tumor progression." (PMID 41359051, 2025). "On the other hand, targeting m6A “erasers” such as ALKBH5 or FTO, which regulate immune checkpoint molecule expression by demethylating m6A modifications, could suppress immune suppression and promote anti-tumor immune responses." (PMID 39911396, 2025). "Furthermore, ALKBH5 downregulation significantly decreased expression of SOX2 and the tumor sphere formation frequency of GBM stem‐like cells (GSCs) derived from NFHDCD cells (NFHDCD‐GSCs)." (PMID 39974663, 2025). "Depletion of m6A demethylases, particularly ALKBH5, under hypoxia leads to the upregulation of CXCL10, which may impact tumor progression and immune response dynamics." (PMID 39824841, 2025). "Collectively, these findings demonstrate that ALKBH5 is not merely a “demethylase” but rather a multidimensional regulator of RNA metabolism and cellular homeostasis, with implications extending from tumor biology to metabolic diseases." (PMID 41562066, 2025). "In NPC, ALKBH5 cooperated with YTHDF1 to stabilize WNT2 mRNA and elevate WNT2 protein levels, which not only promoted M2 polarization of TAMs but also enhanced tumor cell proliferation and metastasis via autocrine activation of the FZD2/β-catenin axis, establishing a vicious cycle." (PMID 41562066, 2025). "By interfering with ALKBH5 expression, this study further explored its role in OC, revealing that ALKBH5 may regulate ITGB1 m6A modification, thereby affecting tumor cell proliferation and apoptosis." (PMID 40585991, 2025). "Our results found that targeting ALKBH5 expression impaired GBM proliferation and tumor stemness." (PMID 39974663, 2025). "The interaction between ALKBH5 and RBPs appears to contribute to its substrate selectivity, and current evidence suggests that this mechanism is largely tumor-specific rather than universal." (PMID 41562066, 2025).
tumor (continued). "The highly expressed ALKBH5 reduces the m6A modification of PVT1 to suppress the YTHDF2-mediated m6A-dependent degradation, leading to PVT1 overexpression, which results in the promotion of OS cell proliferation and tumor growth." (PMID 40958857, 2025). "Secondly, we unveil a novel mechanism of immune evasion of GC cells: HSPA4 overexpression in GC cells decreases CD58 via ALKBH5/CD58 pathway, activates PD1/PDL1 axis, decreases cytotoxicity and infiltration of CD8+ T cells and induces tumor immunosuppressive microenvironment." (PMID 38589927, 2024). "ALKBH5 and FTO act as double-edged swords, which are upregulated in BC and AML and can exert pro-oncogenic effects by regulating mRNAs with transcription factors, but FTO is tumour suppressive for GBM." (PMID 38711100, 2024). "The reintroduction of ALKBH5 into the USP36-deleted GSC cells significantly mitigated the inhibitory impact observed with USP36 knockout, particularly in cell proliferation, stemness, and tumor growth of the GSC cells." (PMID 38398118, 2024). "However, ALKBH5 is increased in lung adenocarcinoma and reduces the m6A level of FOXM1 mRNA, contributing to an oncogenic role in tumor proliferation and invasion." (PMID 39457524, 2024). "In addition, ALKBH5 is upregulated and CD58 is downregulated in tumor tissues with HSPA4 upregulation." (PMID 38589927, 2024). "SOX2OT could recruit ALKBH5 and ALKBH6 to bind to SOX2 and demethylate the SOX2 transcript and subsequent SOX2 up-regulation, thereby regulating tumour cell apoptosis, cell proliferation, and TMZ resistance." (PMID 38055673, 2023). "ALKBH5 regulates lncRNA TP53TG1 and NEAT1, promoting tumor proliferation and metastasis." (PMID 38007439, 2023). "ALKBH5 could maintain FOXM1 mRNA stability by demethylating its nascent transcripts in GSCs, leading to tumor growth." (PMID 37821870, 2023). "ALKBH5 and FTO exhibit distinct regulatory roles in hypoxic tumours." (PMID 36859310, 2023). "Because we surprisingly found that both “writers” (METTL3, METTL14 and WTAP) and “erasers” (ALKBH5 and FTO) could abnormally overexpressed and exert oncogenic functions or downregulated and play tumour suppressor roles in urologic tumours." (PMID 37284313, 2023). "Collectively, this study found that YY1 was regulated by ALKBH5 and YTHDF1-mediated m6A modification and served as an autophagy-dependent tumor driver to accelerate cancer progression through ATG4B transactivation, providing an exploitable therapeutic target for GC." (PMID 37724907, 2023). "In vitro radiosensitivity rescue experiments showed that the radiosensitivity induced by ALKBH5 or YTHDF2 could be reversed by circAFF2, which was confirmed in grafted tumours." (PMID 37381158, 2023). "We also conducted qPCR to determine ALKBH5 and HIF-1α mRNA expression levels in tumor samples." (PMID 36632222, 2023). "Another m6A modifier, ALKBH5, is stabilized by the deubiquitinase USP36 in GSCs, stimulating tumor growth and TMZ resistance, and this USP36–ALKBH5 relationship may provide another targetable scaffold in GSCs." (PMID 37444568, 2023). "Similarly, despite the fact that most studies have demonstrated that ALKBH5 is an oncogene in NSCLC, another work reported its tumor-suppressive role in NSCLC." (PMID 37919739, 2023). "Moreover, FTO and ALKBH5 negatively regulated METTL3 and positively regulated METTL14 expression levels, enhancing their role as tumor suppressors of CRC." (PMID 37580808, 2023). "Additionally, inhibitors against FTO, ALKBH5, IGF2BP1, and ADAR1 have shown promising anti-tumor properties in vitro and in vivo." (PMID 38071304, 2023). "FTO expression was evidently increased in tumor stem-like cells (P < 0.05); however, there was no significant change in the expression level of ALKBH5 (P > 0.05)." (PMID 35568876, 2022).